CCNB1 (cyclin B1)
Diseases named in the same sentence as CCNB1 in open-access papers (continued):
Sharing a sentence is not in itself a finding about the gene and the disease.
colorectal cancer (63 papers, 2010 to 2025). A primary or metastatic malignant neoplasm that affects the colon or rectum. "CCNB1, a crucial member of the cell cycle protein family, promotes the transition from G2 phase to mitosis and has been implicated in the proliferation of colorectal cancer cells." (PMID 39087856, 2024). "Taken together, these results clearly demonstrated that low Cyclin B1 level is associated with poor prognosis and unfavorable clinical outcome of colorectal cancer." (PMID 25962181, 2015). "To evaluate the prognostic potential of Cyclin B1 in colorectal cancer, we analyzed the association between Cyclin B1 expression and survival duration using Kaplan-Meier analysis with log-rank test." (PMID 25962181, 2015). "The Kaplan-Meier survival analysis proved that low Cyclin B1 expression was associated with poor overall survival of patients with colorectal cancer." (PMID 25962181, 2015). "Nuclear localization of cyclin B1 overexpression is associated with poor outcome in carcinoma of oral cavity, esophagus, breast, lung and colorectal cancer." (PMID 23722120, 2013). "Additionally, HMMR is related to prostate cancer, while RRM2 and CCNB1 shared association with colorectal cancer." (PMID 39118438, 2024). "CCNB1 inhibition causes apoptotic death in certain colorectal cancer cells." (PMID 33925358, 2021). "We have observed an increase in Cycline B1 expression in Caco-2 cells induced by extracts, this may be considered positive, since low Cyclin B1 level is associated with poor prognosis and poor clinical outcome of colorectal cancer." (PMID 33339392, 2020). "This meta-analysis indicated that positive/high expression of cyclin B1 may have a close association with worse survival in patients with esophageal cancer, but better prognosis in patients with colorectal cancer." (PMID 29221213, 2017). "Interestingly, cyclin B1 overexpression was linked to favorable 5-year OS of colorectal cancer (OR = 0.49, 95% CI = 0.30 to 0.82, P = 0.006)." (PMID 27903976, 2017). "However, elevated expression of cyclin B1 was associated with better 5-year OS of colorectal cancer." (PMID 27903976, 2017). "Cyclin B1, which associates with cdc2 and leads cells to enter mitosis, was decreased in both EA-treated ovarian carcinoma cells, similar to the result observed in Caco-2 colorectal cancer cells." (PMID 23843871, 2013). "In vitro, CCNB1 knockdown triggered cell cycle arrest, thereby suppressing the proliferation of colorectal cancer cells." (PMID 41614789, 2025). "Multiple investigations have documented elevated expression of CCNA2 and CCNB1 in colorectal cancer." (PMID 41614789, 2025). "Previous studies have shown that CCNB1 promotes the proliferation of colorectal cancer cells, thus exerting an oncogenic effect." (PMID 39087856, 2024). "Our results demonstrated that roburic acid effectively suppressed colorectal cancer cell proliferation by inducing G0/G1 cell cycle arrest and downregulating the protein expression of Cyclin B1, Cyclin D1, and Cyclin E1." (PMID 35222445, 2022). "CCNB1, an important protein regulating the G2/M (mitotic) cell cycle, is activated by Chk1, exerting its oncogenic role in colorectal cancer cells growth in vivo and in vitro." (PMID 33767726, 2021). "High CCNB1 expression is seen in a diverse number of cancers, including esophageal, gastric and colorectal cancers." (PMID 32219041, 2020). "Results from human colorectal cancer have shown that overexpression of CCNB1 induced by Chk1 accelerates cancer cell proliferation and tumor growth." (PMID 32775402, 2020). "In gastric, breast, and colorectal cancer cells, inhibition of CCNB1 induced G2/M phase cell cycle arrest and promoted apoptosis." (PMID 33221765, 2020). "Overexpression of CCNB1 was found in many different diseases, including colorectal cancer, breast, pancreatic cancer, and meningioma." (PMID 28969025, 2017).
colorectal cancer (continued). "In studying the possible mechanism by which Cyclin B1 suppresses colorectal cancer invasion and metastasis, we observed that suppression of Cyclin B1 decreased the expression of E-cadherin protein level." (PMID 25962181, 2015). "Inhibition of Cyclin B1 in colorectal cancer cells enhanced the cell migration and invasion of three different colorectal cancer cell lines." (PMID 25962181, 2015). "In our previous study, we also found overexpression of Cyclin B1 promoted cell proliferation and tumor growth in human colorectal cancer." (PMID 25962181, 2015). "In this study, we found Cyclin B1 expression level in colorectal cancer tissues was also higher than that in nomal tissues in a large panel of 150 patients, consistent with our previous data." (PMID 25962181, 2015). "Here, we demonstrated that the invasion and metastasis of colorectal cancer is regulated by Cyclin B1." (PMID 25962181, 2015). "Our study also revealed inhibition of Cyclin B1 suppressed the expression of E-cadherin, and subsequently led to the induction of migration and invasion of colorectal cancer cells." (PMID 25962181, 2015). "On the basis of our previous published data and our current observations, we suggest that Cyclin B1 is overexpressed and promotes cell proliferation during the early stage of colorectal cancer development." (PMID 25962181, 2015). "We previously found that Cyclin B1 was overexpressed and important for cell proliferation and tumor growth via promoting cell cycle progression and/or reducing apoptosis in colorectal cancer cells." (PMID 25962181, 2015). "In summary, this study provides new insight into the role of the Cyclin B1 in colorectal cancer metastasis." (PMID 25962181, 2015). "To investigate the potential effect of Cyclin B1 on cell invasion in colorectal cancer cells, we used the Matrigel Invasion assay for detection." (PMID 25962181, 2015). "Our finding that the low level of Cyclin B1 expression promoted colorectal cancer metastasis by regulating E-cadherin highlights the potential of Cyclin B1 as a novel agent against colorectal cancer metastasis." (PMID 25962181, 2015). "In this study, we showed that Cyclin B1 suppressed colorectal cancer invasion and metastasis through regulation of E-cadherin expression." (PMID 25962181, 2015). "Overexpression of Cyclin B1 was observed in colorectal cancer tissues, but this elevated expression was negatively associated with lymph node metastasis, distant metastasis stage, and TNM stage." (PMID 25962181, 2015). "To test the impact of YBX1 on CCNB1 expression in colorectal cancer cells, we transiently silenced YBX1 expression in HCT116 cells by RNA interference." (PMID 21170361, 2010). "Chromatin immunoprecipitation using NFY-A, NFY-B or YBX1 antibodies, respectively, revealed that YBX1 preferentially regulates CCNB1 transcription in colorectal cancer cells." (PMID 21170361, 2010). "The expression of YBX1 in primary colorectal carcinomas correlated well with the expression of YBX1 target genes including CCNB1, which are involved in cell cycle control." (PMID 21170361, 2010). "Inhibiting the expression of CCNB1 promotes apoptosis in colorectal cancer cells." (PMID 36291764, 2022). "Previous studies have reported that CCNB1 could participate in oncogene pathways among many kinds of cancers, such as BC and colorectal cancer." (PMID 34384030, 2021). "Interestingly, cleaved PARP was augmented by the downregulation of RBM22 and U2AF1, suggesting that RBM22 and U2AF1 inhibited apoptosis and promoted the tumor progression in colorectal cancer cells through cyclin B1 and/or cyclin D1-dissociated mechanisms." (PMID 34202873, 2021).
colorectal cancer (continued). "Inhibiting the expression of CCNB1 using siRNAs promotes apoptosis in colorectal cancer cells." (PMID 31681566, 2019). "In contrast, upregulation of cyclin B1 reverses metastasis in colorectal cancer cells." (PMID 31126091, 2019). "We examined the action mechanism of B220 in the colorectal carcinoma HCT116 cell line, and found that treatment of cells with B220 caused cells to accumulate in G2/M phase, with a concomitant induction of the mitotic phase markers, MPM2 and cyclin B1." (PMID 28963527, 2017). "However, interestingly, patients with positive/high expression of cyclin B1 had worse prognosis in patients with esophageal carcinoma, but better prognosis in patients with colorectal carcinoma." (PMID 29221213, 2017). "Interestingly, we found that overexpression of Cyclin B1 in colorectal cancer was negatively correlated with lymph node metastasis, distant metastasis, TNM stages, and poor survival." (PMID 25962181, 2015). "Furthermore, a difference in levels of cyclin B1, an indicator of the outcome of cell cycle delay induced by Aurora A kinase inhibitor alisertib, was also observed in double-mutant colorectal cancer cell lines." (PMID 26136684, 2015). "Clinicopathological characteristics and Cyclin B1 expression in colorectal cancer patients." (PMID 25962181, 2015). "Thus, similar as other papers, our results suggest Cyclin B1 favors tumor growth but inhibits metastasis in colorectal cancer." (PMID 25962181, 2015). "Our findings suggest that Cyclin B1 could suppress the invasion and metastasis of colorectal cancer cells through regulating E-cadherin expression, which enables the development of potential intervention strategies for colorectal cancer." (PMID 25962181, 2015). "Then the 150 patients with colorectal cancer were divided into two groups: high Cyclin B1 expression group (n = 88) that Cyclin B1 expression ratio ≥ 3.33, and low Cyclin B1 expression group (n = 62) that Cyclin B1 expression ratio < 3.33, according to the cut-off level." (PMID 25962181, 2015). "Given that Cyclin B1 negatively correlated with enhanced colorectal cancer cell migration and invasion, we examined whether EMT is an underlying mechanism." (PMID 25962181, 2015). "Collectively, these results suggest Cyclin B1 inhibits invasion of colorectal cancer cells." (PMID 25962181, 2015). "Thus, we assessed the effect of Cyclin B1 on migration in colorectal cancer cells using Transwell assay." (PMID 25962181, 2015). "Furthermore, CCNB1, which is activated by Chk1, plays an oncogenic function in colorectal cancer cells and may be useful in the development of new colorectal cancer therapies." (PMID 33925358, 2021). "Here, BTG1 overexpression inhibited proliferation, induced differentiation, autophagy, and apoptosis in colorectal cancer cells (p2 arrest might be related to Cyclin B1 and Cdc25B hypoexpression in HCT-15 transfectants, while G1 arrest in HCT-116 transfectants overexpressing p21 and p27." (PMID 27447746, 2017). "Our results showed that CYT-Rx20 induced G2/M arrest in colorectal cancer cells with upregulated expression of cyclin B1, aurora A, and aurora B, and downregulated expression of cdc25A and cdc25C, which collectively could contribute to the inactivation of cdc2." (PMID 28178649, 2017).
colorectal cancer (continued). "We provided evidence that knockdown of Cyclin B1 expression induced more cells to infiltrate through the matrigel and transwell membrance in all three cancer cell lines, demonstrating that Cyclin B1 suppresses colorectal cancer metastasis by negatively regulating cell migration and invasion." (PMID 25962181, 2015). "To determine whether Cyclin B1 expression is an independent indicator of overall survical for colorectal cancer patients, we first used a univariate Cox proportional hazards regression model to estimate the individual hazard ratio for all of the clinicopathological characteristics." (PMID 25962181, 2015). "Thus, we speculate that Cyclin B1 may suppress colorectal cancer invasion and metastasis by inducing E-cadherin expression." (PMID 25962181, 2015). "In contrast, silencing KIF18A showed no apparently influence on protein expression of p21, CDK1 and cyclin B1 in HCT-116 and MC38 CIN- colorectal cancer cells." (PMID 40175357, 2025). "KIF18A knockdown increased the protein expression of p21, and reduced the protein expression of CDK1 and cyclin B1 in NCI-H747, SW620 and CT26 CIN+ colorectal cancer cells, suggesting that KIF18A inhibition triggered G2/M phase arrest." (PMID 40175357, 2025). "AURKA, cyclin B1, and PLK1 proteins were highly upregulated in colorectal cancer SW480 and HCT‐116 cells compared with normal CCD841 cells." (PMID 38425293, 2024). "MicroRNA-532-3p was ectopically overexpressed in colorectal cancer (CRC) cell lines, leading to reduced transcript and protein levels of FOXM1 and cyclin B1, a direct transcriptional target of FOXM1." (PMID 39272919, 2024). "In colorectal cancer, suppressing CTSB expression was found to downregulate Cyclin B1 and upregulate the Cyclin-CDK inhibitory protein P27kip1 in G2 phase, thereby inhibiting tumor growth." (PMID 37768200, 2023). "Via in vitro experiments, CCNA2, CCNB1, and MYC expression was verified in 25 colorectal cancer tissue pairs." (PMID 37504265, 2023). "In 5 independent gastric and colorectal cancer cohorts obtained from GEO and TCGA, RNF112 was negatively correlated with FOXM1 downstream genes, including CKS1, CCNB1, SKP2, and FN1." (PMID 37288663, 2023). "In colorectal cancer, USP39 was reported to stabilize p21 to activate p21/CDC2/cyclin B1 pathway and promote their proliferation." (PMID 36582601, 2022). "A previous study also showed that high expression of CCNB1 and CCNF was significantly correlated with favorable prognosis in colorectal cancer, which is in agreement with our findings." (PMID 33996604, 2021). "Through suppressing cyclin B1 expression, proteasome activator complex subunit 3 (PSME3) triggers cell cycle arrest at the G2/M phase and enhances the radiosensitivity of colorectal cancer cells." (PMID 34462422, 2021). "In both HeLa and human colorectal cancer (HCT 116) cells, SBI‐0206965 decreased the level of cyclin B1 that forms an active complex with CDK1 to initiate mitotic entry." (PMID 33040463, 2020). "The expression of cdc-2 and cyclin B1 was reduced after re-expression of RASSF10 in RKO and HCT116 cells, providing a mechanism by which RASSF10 induces G2/M arrest in colorectal cancer." (PMID 25638156, 2015). "The association between Cyclin B1 level and clinicopathological characteristics showed the expression of Cyclin B1 was negatively correlated with lymph node metastasis, distant metastasis, and advanced TNM stage (P = 0.007) in patients with colorectal cancer." (PMID 25962181, 2015). "These experiments confirmed that sites highly enriched in SOX9 binding overlap the NF-YA binding sites around the TSSs (within 500 bp of TSSs) of TOP2A, CCNB1, CCNB2 and CDK1 in colorectal cancer cells." (PMID 26040697, 2015). "This robust subset of YBX1 targets included CCNB1, supporting the crucial role of YBX1 in proliferation control in colorectal cancer." (PMID 21170361, 2010).
colorectal cancer (continued). "Similarly, AM-1882 treatment promoted the protein expression of p21, and suppressed the protein expression of CDK1 and cyclin B1 in NCI-H747, SW620 and CT26 CIN+ colorectal cancer cells." (PMID 40175357, 2025). "Similarly, in the research focusing on DSN1 expression and colorectal cancer progression, evidences also showed that down-regulating of DSN1 favor cyclin B1 expression and increase G2M arrest, which is in accordance with the research conclusion drawn above." (PMID 34131395, 2021). "Univariate analysis demonstrated that Cyclin B1 was a prognostic indicator for overall survival in patients with colorectal cancer, though multivariate analysis showed Cylcin B1 was not an independent prognostic factor." (PMID 25962181, 2015). "To identify the potential role of Cyclin B1 in colorectal cancer metastasis, we initially examined the expression of Cyclin B1 in 150 pairs of colorectal cancers and matched adjacent non-tumor colorectal tissues using qRT-PCR." (PMID 25962181, 2015). "In addition, CYT-Rx20 induced cell cycle arrest of colorectal cancer cells at the G2/M phase and upregulated the protein expression of phospho-ERK, cyclin B1, phospho-cdc2 (Tyr15), aurora A, and aurora B, while it downregulated the expression of cdc25A and cdc25C." (PMID 28178649, 2017). "However, the role and mechanism of Cyclin B1 in colorectal cancer metastasis has not been well studied." (PMID 25962181, 2015). "Moreover, we also confirmed the protein level of Cyclin B1 in 30 clinical tissues samples, including 10 normal colorectal tissues, 10 colorectal cancer tissues without metastasis, and 10 cancer tissues with metastasis by western blot." (PMID 25962181, 2015). "However, absence of prognostic relevance or favorable prognosis of Cyclin B1 was also observed in colorectal cancer, lymphoma and pancreatic neuroendocrine tumor." (PMID 25962181, 2015). "Consistently, CCNA2, CCNB1, CCND1, and CCNF have been observed to be upregulated in colorectal cancer, but there is no clear evidence that CCNE1 and CCNJL are also differentially expressed between colon tumor and normal tissues." (PMID 33996604, 2021).